BDNF (brain derived neurotrophic factor)
Diseases named in the same sentence as BDNF in open-access papers (continued):
Sharing a sentence is not in itself a finding about the gene and the disease.
Cognitive impairment (continued). "Previous studies have found significant correlations between hyperglycemia and DPP4 activity, BDNF and cognitive impairment, to exclude the possible influences of hyperglycemia on DPP4 activity, BDNF and cognitive function." (PMID 30886577, 2019). "Psychotropic medications, especially for treating cognitive disorder and major depressive disorder (MDD), have been shown to affect serum BDNF levels." (PMID 30634650, 2019). "Additionally, nobiletin, an active ingredient in Pericarpium Citri Reticulatae, may ameliorate isoflurane-induced cognitive impairment and delay the aging process through antioxidant, anti-inflammatory and antiapoptotic effects via modulation of Akt, Bax, pCREB and BDNF in aging rats." (PMID 31730453, 2019). "At the cellular level, increases in BDNF may be the link between exercise and learning; however, BDNF induction in response to acute exercise is mixed, and may be influenced by the intensity of exercise, along with the level of cognitive impairment among research participants." (PMID 31920835, 2019). "Thus, low BDNF might be an effective biomarker for diabetes related cognitive impairment." (PMID 29484146, 2018). "Cholinergic dysfunction, impaired brain-derived neurotrophic factor and cAMP response element binding protein (BDNF-CREB) signaling are one of the major pathological hallmarks of cognitive impairment." (PMID 30018265, 2018). "Interestingly, postmortem studies have shown that BDNF mRNA and protein decrease not only in end‐stage disease, but also in patients diagnosed with mild cognitive impairment (MCI), suggesting that a BDNF loss could be involved in the early synaptic dysfunctions." (PMID 29094448, 2018). "Our previous study found both cognitive impairment and decreased BDNF serum levels in T2DM patients, as well as a positive correlation between delayed memory and BDNF levels in these patients." (PMID 29423073, 2018). "Fucosterol co-infusion attenuated sAβ1-42-induced cognitive impairment in aging rats via downregulation of GRP78 expression and upregulation of mature brain-derived neurotrophic factor expression in the dentate gyrus." (PMID 30301140, 2018). "Also, we found the BDNF-Met allele carrier exhibited a poorer delayed memory index score than their Val counterparts in T2DM patients, suggesting that the BDNF Val66Met polymorphism was involved in some domains of cognitive deficits in T2DM patients but not in healthy subjects." (PMID 29423073, 2018). "In our study, the absence and structural damage of neuronal cells resulted in inhibition of BDNF-TrkB in the APP/PS1 group, appearing cognitive impairment which performance as learning and memory dysfunction." (PMID 29980225, 2018). "In summary, we have demonstrated that SE-EE possess anti-amnesic effects and regulates behavioral-cum-cognitive deficits in scopolamine-induced AD-like mice, possibly by enhancing hippocampal neurogenesis through the regulation of CREB/BDNF signaling." (PMID 29740000, 2018). "Various cognitive defects that were induced in rat models were reversed following the treatment of resveratrol by inhibiting TNF-α and IL-1β levels and elevating BDNF levels in the hippocampus." (PMID 30262792, 2018). "Any changes or alterations of neurotrophic factor level such as BDNF, NGF, and GDNF are related to cognitive deficit or impairment." (PMID 29200666, 2017). "The rescue of cognitive impairment by P021 treatment found in the present study is consistent with similar beneficial effects shown previously with 7,8-DHF and other BDNF agonist compounds." (PMID 28655344, 2017). "Meanwhile, increased BDNF may not be associated with cognitive impairment." (PMID 28403087, 2017). "Improved attention and working memory in animal models and patients with mild cognitive impairment, increased the levels of NGF and BDNF in rats." (PMID 26941642, 2016).
Cognitive impairment (continued). "Parallel to the time course of cognitive deficit development, PFC BDNF expression was quantified 1 week after the stress and 6 weeks later during adulthood." (PMID 27757074, 2016). "Our lab found that NSC transplantation into the hippocampus of 3xTg-AD mice increases synapse density and reverses cognitive deficits, and these benefits are mediated by NSC-derived BDNF." (PMID 22870188, 2012). "Both IF and exercise partially reversed cognitive impairments by reducing sAβ and oxidative stress, increasing BHB, suppressing NF-κB/NLRP3 signaling, and restoring BDNF (p < 0.05), while fasted-state exercise produced significantly larger effects than either intervention alone (p < 0.05)." (PMID 42152587, 2026). "In our study, in vivo experiments demonstrated that the supplementation of hesperetin with metformin elevated acetic acid, propionic acid, and butyric acid content, leading to improved cognitive impairment in DM rats through the protection of insulin signaling and the activation of CREB/BDNF." (PMID 40076550, 2025). "A compelling aspect of BDNF gene therapy is its capacity to reverse cognitive impairment in the absence of amyloid or tau reduction." (PMID 40656325, 2025). "Additionally, TEN alleviates Aβ protein‐induced decreases in BDNF and PSD‐95 expression levels in the HT‐22 cell line and ameliorates Aβ protein‐induced cognitive deficits in mouse models." (PMID 40873250, 2025). "Additionally, the absence of a seronegative control group hinders the establishment of baseline BDNF levels in this population, which is important for future research and for validating BDNF as a biomarker for HIV-related cognitive impairment." (PMID 39548055, 2025). "Previous research has also identified a link between lifetime suicide attempts (LSA) and both cognitive deficits and altered BDNF levels, with suicide attempters often exhibiting worse cognitive performance and lower BDNF concentrations than non-attempters." (PMID 40264519, 2025). "There was no clear finding that silkworm pupae can change hippocampal BDNF expression, but silk fibroin enzyme hydrolysate was reported to increase the expression of BDNF in a scopolamine-induced cognitive deficit model." (PMID 40720390, 2025). "We hypothesized that niacin supplementation may alleviate WBI-induced behavioral and cognitive impairments by reducing oxidative stress and inflammation through modulation of the SIRT1/CREB/BDNF and SIRT1/SIRT6 signaling pathways." (PMID 40508105, 2025). "A recent cross-sectional comparative study (208 healthy control subjects, 123 patients with mild cognitive impairment (MCI), and 123 patients with schizophrenia) also reported a lower concentration of plasma BDNF levels in patients with schizophrenia and MCI compared with those in healthy controls." (PMID 40005159, 2025). "The Western blot analysis of the SCO-induced cognitive impairment mouse model was performed to determine whether SHE administration activated the ERK/CREB signaling pathway and promoted BDNF expression to improve cognitive function." (PMID 40949138, 2025). "Studies using sophisticated two-photon imaging have demonstrated that BDNF can reverse synaptic disorganization and atrophy in amyloid exposed hippocampal neurons, culminating in a recovery of LTP deficits and cognitive impairment during hippocampal-dependent tasks." (PMID 40362507, 2025). "By examining these biomarkers within well-defined cognitive subgroups, we aim to determine whether BDNF and CRP levels can serve as potential indicators of cognitive impairment severity or subgroup classification." (PMID 41367212, 2025). "Studies often induce cognitive deficits using scopolamine, aluminum chloride, or insecticides, which disrupt cholinergic signaling and reduce key proteins like CREB (cAMP-response element-binding protein) and BDNF (brain-derived neurotrophic factor (BDNF)." (PMID 40149610, 2025).
Cognitive impairment (continued). "Additionally, it has been found that exercise can improve cognitive deficits in ovalbumin (OVA)-sensitized rats, increase BDNF levels, and enhance LTP in the hippocampus of OVA-sensitized rats." (PMID 40831583, 2025). "In individuals with mild cognitive impairment (MCI) and dementia, we have investigated BDNF Val66Met genotype distribution, peripheral BDNF DNA methylation, mRNA and protein levels, and cognitive performance using the Mini-Mental State Examination (MMSE) and Clock Drawing Test (CDT)." (PMID 41009553, 2025). "The serum BDNF levels in T2DM with cognitive impairment group had a marginal difference from those without cognitive impairment [SMD: -2.59, z = 1.87, P = 0.06]." (PMID 38648255, 2024). "Excess copper plays an important role in cognitive impairment, as demonstrated in an experimental model by blocking cAMP response element-binding protein (CREB), leading to decreased expression of its downstream target brain-derived neurotrophic factor (BDNF)." (PMID 39062119, 2024). "Some studies reported a correlation of high BDNF levels with improvement of memory and correlation of decreased BDNF concentrations with mild cognitive impairment even in newly diagnosed pwMS with no or mild disability." (PMID 39148705, 2024). "In this context, the aim of our study was to evaluate intraplatelet levels of BDNF in a sample of adult autistic subjects without intellectual impairment and healthy controls." (PMID 39062102, 2024). "In the present meta-analysis, the serum BDNF levels presented a decreasing tendency in T2DM patients with cognitive impairment compared with those patients without cognitive impairment." (PMID 38648255, 2024). "Moreover, brain-derived neurotrophic factor (BDNF), which is a crucial player for neurodevelopment and cognitive functions, showed lower levels in ACE2KO mice, with higher ATR1 expression and cognitive deficits." (PMID 38641847, 2024). "According to previous studies, brain-derived neurotrophic factor (BDNF) decreases and DPP4 activity increases in the peripheral circulation of mild cognitive impairment, and the negative correlation is caused by oxidative stress and inflammation." (PMID 38379936, 2024). "BDNF might be involved in the neuropathophysiology of cerebral damage in T2DM, especially cognitive impairment in T2DM." (PMID 38648255, 2024). "ANA12 prevents LPS-induced cognitive deficit-like behavior, probably because ANA12 may prevent dysregulated BDNF from activating TrkB signals interrupting NKCC1 and KCC2 in the hippocampus and prefrontal cortex." (PMID 38539677, 2024). "Consequently, downstream brain‐derived neurotrophic factor (BDNF) expression is diminished, ultimately impairing synaptic plasticity and neurogenesis of hippocampal neurons and contributing to cognitive deficits observed in depressed individuals." (PMID 39119889, 2024). "Excessive hypocretin‐1 conducted with hypocretin receptor 1 (HCRTR1) reduced lactate production and brain‐derived neurotrophic factor (BDNF) expression by hypoxia‐inducible factor‐1α (HIF‐1α), thus impairing adult hippocampal neuroplasticity, and cognitive impairment in CUMS model." (PMID 39119889, 2024). "HFD also impairs hippocampal neurogenesis, maybe through increased methylation of the brain-derived neurotrophic factor (BDNF) gene promoter on spermatozoa, with resulting cognitive impairment in the F1 generation." (PMID 38534435, 2024). "We evaluated whether FPF could increase the BDNF expression in the hippocampus and investigated the involvement of BDNF signaling on the improving effect of FPF on cognitive impairment by using ANA12, a TrkB receptor antagonist." (PMID 39683616, 2024). "Our results indicate that cognitive impairment following EHS may be a consequence of thermal injury-induced disruptions in gut microbiota and metabolism, which in turn lead to diminished BDNF expression in the hippocampus via the gut-brain axis." (PMID 38654189, 2024).
Cognitive impairment (continued). "Thus, interventions that raise BDNF and IGF-1 levels are expected to become potential targets for the treatment of cognitive impairment and Alzheimer’s disease in the near future." (PMID 38961824, 2024). "Piromelatine (50 mg/kg, i.p.)also exhibited a positive effect in ameliorating cognitive deficits in AD model mice, although changes in BDNF levels were not reported." (PMID 39500357, 2024). "Overexpression of SIRT1/BDNF and specific activation of glutamatergic neurons in the hippocampal CA1 region have the potential to restore synaptic plasticity and improve postoperative cognitive impairment." (PMID 38783169, 2024). "The serum BDNF levels in T2DM patients with cognitive impairment had a downward trend compared with those patients without cognitive impairment." (PMID 38648255, 2024). "In conclusion, manipulating brain BDNF content through non-pharmacological interventions such as EX has emerged as a promising strategy to enhance cognitive function and mitigate cognitive deficits." (PMID 37868812, 2023). "Although over-expression of BDNF improves cognitive deficits in AD animal models, bioavailability and blood–brain barrier permeability of BDNF is poor, and it is invasive and not practical to inject the BDNF-expressing lentivirus into the human brain." (PMID 36830589, 2023). "Taken together, gossypetin may serve as a novel compound in the treatment of cognition impairments in T2DM due to its ability to reduce oxidative stress and inflammation, decrease cortisol levels and increase BDNF levels." (PMID 38139436, 2023). "The results suggest that BDNF does not play a mediatory role in the pathophysiology of cognitive impairment in T2DM." (PMID 36936159, 2023). "These suggested that LV-GPR17–shRNA and cangrelor improve cognitive impairment induced by LPS and might be involved in the CREB/BDNF signaling in mice." (PMID 37990234, 2023). "Treatment of amyloid-transgenic mice by injection of lentivirus-BDNF into hippocampal entorhinal cortex after disease onset prevented cell death and ameliorated cognitive deficits, independent of direct modulation of amyloid." (PMID 37369719, 2023). "MTX-induced neurotoxicity and cognitive impairment could be attributed to the microglial activation and neuroinflammatory response in part through the miR-15a/ROCK-1/ERK1/2/CREB/BDNF cascade." (PMID 36943623, 2023). "Importantly, cognitive impairment in patients with T2DM manifest in a variety of ways, including reduced levels of cognitive markers such as BDNF, decreased information processing speed, and impaired performance during the dual-task gait test." (PMID 37649720, 2023). "A decrease in pro-inflammation cytokine concentrations and an increase in the expression levels of SIRT1, BDNF, PSD-95, and SYP in the hippocampus following resveratrol treatment contributed to reducing the cognitive deficits in offspring mice resulting from maternal immune activation." (PMID 38074521, 2023). "NfL/BDNF ratio was higher in SUD patients with moderate/severe cognitive impairment compared with AUD patients without cognitive impairment (p = 0.012) or mild cognitive impairment (p = 0.018)." (PMID 36674698, 2023). "Overall, the BDNF plasma levels were not significantly different when comparing the patients with a normal cognition to those who had a cognitive deficit (p = 0.22)." (PMID 37445746, 2023). "Further study with expanded sample size and follow-up investigations should be carried out to establish if cytokines, BDNF, and the SBM indices are involved in the process of compensating for cognitive function ahead of the onset of T2DM-related cognitive impairment." (PMID 37113152, 2023). "Supplementation with LP EMCC-1039 may improve NAFLD and cognitive impairment by affecting the intestine–liver–brain axis and hippocampal TLR4/BDNF signaling pathway." (PMID 37249983, 2023).
Cognitive impairment (continued). "Here we demonstrate a potential anti-diabetic drug that increases BDNF levels in terms of gene expression and serum protein levels, which may help to comprehend better treatment regimens for T2DM patients with cognitive impairment." (PMID 38001940, 2023). "Here, we evaluate the therapeutic potential of irradiated engineered human mesenchymal stem cells over-expressing brain-derived neurotrophic factor (BDNF), which we denote by BDNF-eMSCs, in protecting the brain against neuronal death, neurological deficits, and cognitive impairment in TBI rats." (PMID 36986535, 2023). "Recently, brain derived neurotrophic factor (BDNF), dipeptidyl peptidase-4 (DPP4), and Ca2+ brain dysregulation were identified as novel biomarkers and potential therapeutic targets for diabetes-related cognitive impairment." (PMID 35958117, 2022). "However, the cognitive impairment was partially reversed by moderate physical activity, revealing a recovered PGC1α/ FNDC5/BDNF pathway." (PMID 35764750, 2022). "It was preliminarily found that plasma BDNF concentrations were related to AD cognitive impairment but not a simple linear relationship." (PMID 36425322, 2022). "So, these results indicate that the increase in BDNF is positively correlated to more severe cognitive impairment in non-responders." (PMID 36248031, 2022). "Moreover, genistein improves cognitive disorders, and reduces MCP-1 release, and elevates the levels of IL-10, IGF-1, BDNF, and CREB in the hippocampus of hypoxia-induced mice." (PMID 36353622, 2022). "However, there is limited knowledge regarding the effects of CCRT combined with aerobic exercise on cognitive function and brain-derived neurotrophic factor (BDNF) levels in patients with schizophrenia and cognitive impairment." (PMID 36261468, 2022). "The purpose of this study is to measure BB-DNA in healthy elderly controls (EC), and in patients with mild cognitive impairment (MCI) and AD to explore the effect on plasma BDNF levels (pBDNF), the inflammatory response, and the association with cognitive decline during a two-year follow-up." (PMID 36613538, 2022). "Cognitive function was also found to be significantly worse in patients, however, correlations between BDNF levels and cognitive impairment were not always detected." (PMID 35686181, 2022). "The genes of cognitive impairment modified by histone include GAD1, GAD2, NMDAR, CACNA1H, and BDNF." (PMID 36406755, 2022). "BDNF first decreased and then increased with cognitive impairment in the ApoE4-negative group (P < 0.05), and there was no significant change in BDNF with cognitive impairment in the ApoE4-positive group (P > 0.05)." (PMID 36425322, 2022). "BDNF increased gradually with cognitive impairment in the Shanghai group (P = 0.010), and there was no significant change in cognitive impairment in other districts (P > 0.05)." (PMID 36425322, 2022). "BDNF increased gradually with cognitive impairment in the group with 0–6 years of education (P < 0.05), and there was no significant change in BDNF with cognitive impairment in the other two groups (P > 0.05)." (PMID 36425322, 2022). "In summary, we demonstrated that resveratrol treatment alleviated pain behaviors and ameliorated cognitive deficits in rats with cobra venom-induced trigeminal neuralgia, possibly by restoring the ultrastructure of neurons and synapses and increasing the CREB/BDNF expression in the hippocampus." (PMID 36478990, 2022). "Patients with an earlier age of onset have shown more negative symptoms and cognitive deficits, as well as lower levels of serum BDNF." (PMID 34220575, 2021). "However, oral administration of NK210, NK219, or Mx decreased cognitive impairment-like behaviors, NF-κB+/Iba1+ cell population, and TNF-α and IFN-γ expression in the hippocampus, while BDNF+/NeuN+ cell population and IL-10 expression increased." (PMID 34667205, 2021).